PPARA (peroxisome proliferator activated receptor alpha)
Diseases named in the same sentence as PPARA in open-access papers (continued):
Sharing a sentence is not in itself a finding about the gene and the disease.
dyslipidemia (continued). "The reduction in PPARα activity in SF mice, coupled with dyslipidemia, may, therefore, be contributing to worsening autoimmunity, inflammation, and hepatitis." (PMID 38398835, 2024). "Interestingly, inflammation is reduced with fenofibrate treatment, a PPARα agonist used to treat dyslipidemia." (PMID 39684525, 2024). "Previous studies have demonstrated the critical role of PPARα in ameliorating hyperlipidemia through lipoprotein metabolism, which suggests that limonene may protect against dyslipidemia through regulation of PPARα signaling." (PMID 37299525, 2023). "In 2015, the PPARα/γ agonist, saroglitazar, was reported to be of substantial benefit for patients with atherogenic dyslipidemia and/or diabetes, and in 2017 therapy with statin plus K-877 (pemafibrate) was advocated as therapy with a favorable benefit-to-risk ratio." (PMID 37908502, 2023). "8-HEPE activates the PPARα to regulate lipid dyslipidemia and inflammation by inhibiting STAT." (PMID 37630721, 2023). "However, to confirm the usefulness of PPARα agonists for the statin residual CVD risk, well-designed studies focused on subjects with metabolic syndrome or atherogenic dyslipidemia in primary and secondary prevention should be needed in the future." (PMID 35408799, 2022). "Some PPARα-specific agonists, such as Wy14643 and fenofibrate, have been applied in metabolic syndrome treatment, which might own potential in wider application." (PMID 36589809, 2022). "Thus, PPARα signaling pathway is likely the fundamental mechanism of Torularhodin’s function of anti-hepatic dyslipidemia, anti-hepatic inflammation, and other health benefits." (PMID 36234935, 2022). "Isoflavone is a potent agonist of PPARα/γ and exerts anti-inflammatory activity, which may contribute to the prevention of metabolic syndrome." (PMID 35807748, 2022). "PPARα agonists, notably fibrates (e.g., clofibrate, fenofibrate, ciprofibrate, bezafibrate), are used to improve lipid metabolism and insulin sensitivity in metabolic syndrome." (PMID 35565236, 2022). "Early research reported that naturally occurring variations of PPARα function influenced plasma lipid concentrations in type II diabetic patients but not healthy people, demonstrating that PPARα is a link between diabetes and dyslipidemia." (PMID 36589809, 2022). "Studies have also confirmed that wogonin may have beneficial effects in ameliorating dyslipidemia via PPARα activation." (PMID 36061816, 2022). "This is the first report to reveal the PPARα/γ dual agonistic action and glucose uptake enhancing property of AF along with its antiadipogenic effect, indicating its potential in ameliorating the symptoms of metabolic syndrome." (PMID 35163893, 2022). "The modulating effects of PPARα on lipid metabolism and inflammation may explain our finding that PPARα activation modulated dyslipidemia in this diabetic mouse model." (PMID 36992750, 2022). "This demonstrates the link between PPARα and dyslipidemia in diabetes." (PMID 36209101, 2022). "We examined whether exposure to low-dose PFOA and GenX induces metabolic disturbances in mice, including NAFLD, dyslipidemia, and glucose tolerance, and studied the involvement of PPARα." (PMID 36115532, 2022). "In addition, UA functioned as a PPARα agonist to regulate metabolic syndrome, liver diseases, respiratory dysfunction, and exaggerated inflammatory response in the animal and cell line experiments." (PMID 36092543, 2022). "Pemafibrate is a potent selective peroxisome proliferator-activated receptor α (PPARα) modulator that may be safer than conventional PPARα agonists in the treatment of dyslipidemia." (PMID 33997447, 2021). "As a PPAR-α agonist, fenofibrate has been widely used in the treatment of dyslipidemia, it can effectively against NAFLD and improve liver function, and the probable mechanism is that fenofibrate activates PPARα, which can prevent excessive hepatic triglyceride (TG) accumulation." (PMID 35126113, 2021).
dyslipidemia (continued). "We previously showed that the specific PPARα agonist fenofibrate, an FDA-approved drug used to treat dyslipidemia with minimal activity toward PPARγ, upregulated PPARα target genes in the DRG and rescued the impaired axon growth in mice lacking fatty acid synthase in SGC." (PMID 34586065, 2021). "The improving effects of PPARα on lipid metabolism may explain our finding that PPARα activation modulated the STZ-induced dyslipidemia." (PMID 34440028, 2021). "We expected that a compound that effectively activates both PPARα- and PPARδ-subtypes might have additive and/or synergistic positive effect(s) in the treatment of metabolic syndrome." (PMID 34502131, 2021). "However, under fasting conditions or a high-fat diet, Pparα KO mice develop hypoglycemia and dyslipidemia characterized by excessive production of triacylglycerols." (PMID 33799988, 2021). "During empagliflozin administration, the effects of lipid oxidation and PPARα, as well as genetically determined dyslipidemia in HHTg rats, may explain the discrepancies between this study and ours." (PMID 34768942, 2021). "Therefore, for diabetic patients with dyslipidemia, drugs with dual PPARα/PPARγ activity seem to be suitable for treatment." (PMID 33995008, 2021). "Also, subjects with metabolic syndrome significantly decreased PPARα expression in eosinophils by approximately 21%." (PMID 33292260, 2020). "While fenofibrate did not ameliorate liver histology in biopsy-proven NAFLD, a selective PPARα agonist, also known as Pemafibrate, did improve liver function in patients with dyslipidemia, which was previously established in diet-induced murine models of NAFLD." (PMID 32046285, 2020). "Therefore, PPARα has been recognized as a relevant drug target for metabolic syndrome, type 2 diabetes, and coronary atherosclerosis." (PMID 32376995, 2020). "Hence, PPARα agonists have a significant importance in the treatment of dyslipidemia or metabolic syndromes by decreasing triglyceride levels in plasma." (PMID 32536865, 2020). "PPARα/γ agonists have been developed for the management of metabolic syndrome." (PMID 32931724, 2020). "Previously, other group, as well as ourselves, have showed that inhibition of PPARα could alleviate atherogenic dyslipidemia and DCM." (PMID 30635067, 2019). "Especially, fibrates, ligands of PPARα are clinically used to treat dyslipidemia." (PMID 30717248, 2019). "Among three subtypes of PPARs, PPARα and PPARγ have been widely applied in clinic because the related drugs are already available for treating metabolic disease including type II diabetes and dyslipidemia (such as PPARα agonist fibrates and PPARγ agonist thiazolidinediones)." (PMID 31073415, 2019). "Thus, given the favorable safety profile and comparable performance to other fibrates, pemafibrate is a superior PPARα agonist for dyslipidemia." (PMID 31614690, 2019). "Fibrates are PPARα agonists used to treat dyslipidemia, thiazolidinediones (TZDs) are PPARγ agonists used to treat type 2 diabetes, and the glitazars are dual PPARα and PPARγ agonists used to treat dyslipidemia and type 2 diabetes comorbidities." (PMID 30283300, 2018). "Currently, fibrates (synthetic PPARα agonists) are used to treat dyslipidemia, whereas the class of antidiabetic Thiazolidinediones (TZDs) targeting PPARγ had been widely prescribed for the management of T2D but are now partially withdrawn from clinical use due to their side effects." (PMID 29895749, 2018). "The obtained data of the in vivo and in vitro studies suggest that XH601 exhibited strong ability to improve the dyslipidemia in hamsters fed with high-fat diet and the hypolipidemic mechanisms of XH601 were associated with the up-regulation of PPARα and PPARβ/δ expression." (PMID 28464894, 2017).
dyslipidemia (continued). "In a complementary fast food (FF) diet NASH model, mimicking features of the metabolic syndrome, miR-21 levels increase in both liver and muscle, concomitantly with decreased expression of peroxisome proliferator-activated receptor α (PPARα), a key miR-21 target." (PMID 28406477, 2017). "PPARα is a transcription factor that regulates the metabolism of lipids, carbohydrates, and amino acids and is activated by ligands such as drugs used to treat dyslipidemia." (PMID 28464894, 2017). "Since PPARα activation is considered to be valuable for the prevention and improvement of metabolic syndrome, we hypothesized that PPARα activation plays a protective role in debilitating inflammatory and invasive breast cancer progression." (PMID 26621841, 2016). "Agonist ligands for PPARα have been clinically used for atherogenic dyslipidemia management." (PMID 27807394, 2016). "Clinically, fibrates are synthetic PPARα agonists widely used to treat dyslipidemia." (PMID 26770648, 2016). "PPARα agonists, such as fibrates, have been used widely for the treatment of dyslipidemia." (PMID 25885422, 2015). "Moreover, Ppard interaction with hepatic AMPK (phospho-AMP-activated protein kinase), PGC-1α (PPARα-PPARγ coactivator), and lipin-1 refers to them as therapeutic targets in the prevention of dyslipidemia." (PMID 24799886, 2014). "The synthesis of new drug generation - PPARα/γ dual agonists - connecting positive influences on both lipid and glucose metabolism has been recently developed as a response to the treatment challenge of co-existing type 2 diabetes mellitus with dyslipidemia." (PMID 24524207, 2014). "Ligands of PPARα have been used for fighting metabolic syndrome." (PMID 24147098, 2013). "Of the 77 tested compounds, the isoflavones 55a, 55c, 55e and 55i were identified as novel potent dual PPARα and γ agonists, which could serve as future leads in PPAR-related disorders that include type II diabetes mellitus and metabolic syndrome." (PMID 23609624, 2013). "HNF4α might be a dual PPARα/γ activator, and overexpression of HNF4α may be effective in treatment of type 2 diabetes and dyslipidemia and in preventing atherosclerotic cardiovascular disease." (PMID 22190905, 2011). "Since dual PPARα and PPARγ agonists might provide broader beneficial metabolic effects through a simultaneous treatment of hyperglycemia and dyslipidemia, compounds targeting both PPARα and γ have been developed by the pharmaceutical industry." (PMID 20981297, 2010). "Isoflavones are potent dual PPARα/γ agonists and exert anti-inflammatory activity, which may contribute to the prevention of metabolic syndrome, atherosclerosis and various other inflammatory diseases." (PMID 22254019, 2010). "Furthermore, the PPARα agonists gemfibrozil and fenofibrate improve dyslipidemia and insulin sensitivity in humans." (PMID 20825652, 2010). "In addition to PPARγ ligands, PPARα andPPARδ are currently being explored as potentialcardiovascular therapeutics and metabolic syndrome alleviation agents." (PMID 18645617, 2008). "Based on the findings that the glitazone-class antidiabeticagents and fibrate-class antidyslipidemic agents are ligands of PPARγ and PPARα, respectively, much researchinterest has been focused on these two metabolic NR subtypes as therapeutictargets for the treatment of diabetes and dyslipidemia." (PMID 18566690, 2008). "For example, the effect of the PPARα L162V polymorphism on lipid profiles has been studied in middle age subjects with and without endo-phenotypes of metabolic syndrome in three different reports." (PMID 17705849, 2007). "However, there is a need for new drugs with fewer restrictions on use and an excellent benefit-risk balance, and efforts are being made to develop a drug for dyslipidemias that strengthens the effects of PPARα agonists, as represented by fibrate drugs, but has fewer unfavorable adverse effects." (PMID 39802168, 2025).
dyslipidemia (continued). "Therefore, Smilax dominguensis could possess molecules with potential dual agonist activity to PPARα/γ and could restore homeostasis in metabolic disorders such as diabetes, dyslipidemia, and metabolic syndrome." (PMID 39598363, 2024). "In addition, pioglitazone, an agonist of peroxisome proliferator-activated receptor α/γ (PPARα/γ) with the validated efficacy to relieve metabolic syndrome and steatosis, was administrated (1.2 mg/kg/day by gavage) as a positive control in a group of mice for the same period." (PMID 36115008, 2023). "In addition to helping to correct dyslipidemia, PPARα agonists may be helpful in the treatment of cholestatic liver disease, nonalcoholic fatty liver disease, and type 2 diabetes." (PMID 36193146, 2022). "Intriguingly, and of relevance to this work, the addition of PPARα agonistic activity to PPARγ, PPARγ, to PPARδ agonists has led to a higher safety profile, leading to their development for use in many diseases, including type 2 diabetes, dyslipidemia, and non-alcoholic fatty liver disease." (PMID 35288651, 2022). "Furthermore, we summarize recent promising oral therapies in diabetes; fenofibrate and pemafibrate, well-known agonists of peroxisome proliferator-activated receptor alpha (PPARα) in treatments for dyslipidemia and discuss their recent potentials as promising oral DR treatments." (PMID 34682788, 2021). "Thus, pharmacological targeting of PPARα activation may be one of the important strategies for patients with diabetes, metabolic syndrome, obesity, and atherosclerotic CV diseases." (PMID 31974794, 2020). "Similarly, the induction of dyslipidemia in offspring by a maternal low-protein diet (9% vs. 18%) during pregnancy involves an altered epigenetic regulation of specific transcription factors, including PPARα, in the liver of offspring." (PMID 28930193, 2017). "If successful, this next generation of PPARα-agonists has the potential to supersede fibrates as the treatment of choice in patients with atherogenic dyslipidemia and could have a major impact on the management of residual macro- and microvascular risk associated with MetS and T2D." (PMID 23721199, 2013). "For instance, specific PPARβ/δ agonists may increase HDL cholesterol or HDL/LDL cholesterol ratio, and may decrease excess circulating triglycerides and insulin levels, and, like agonistic PPARα and PPARγ ligands, can counteract some of the aspects of the metabolic syndrome." (PMID 22654896, 2012). "Dual PPARα/γ agonists hold promise to be able to combine the properties of TZDs and fibrates, as well as improve the management of type 2 diabetes and provide an effective therapeutic option for treating the multifactorial components of cardiovascular disease, metabolic syndrome, and even cancer." (PMID 21603234, 2011). "Therefore, PPARα agonists suppress dyslipidemia observed in metabolic syndrome." (PMID 20814441, 2010). "Agonists of peroxisome proliferator-activated receptors (PPARα, PPARγ, PPARδ) regulate lipoprotein metabolism, fatty acid oxidation, glucose homeostasis and inflammation, and therefore are used as anti-diabetic drugs for treatment of dyslipidemia and insulin insistence." (PMID 19636418, 2009). "As an established modulator of gene transcription, PPARα regulates the expression of genes knownto be involved in energy metabolism, cellular proliferation, and angiogenesisand to have positive effects on the control of dyslipidemia, inflammation, andcardiovascular diseases." (PMID 18725983, 2008). "Thus, PPARα is a strong candidate gene for the genetic component of metabolic syndrome." (PMID 17705849, 2007). "For example, PPARα agonists (fibrates), PPARγ agonists (thiazolidinediones -TZDs) and combined PPARα/γ agonists (glitazars) are therapeutic agents for CVD prevention, T2DM and dyslipidemia." (PMID 39062500, 2024). "SAB relieved dyslipidemia and hyperglycemia partly by modulating the acetyl-CoA and AMPK/PPARα in db/db mice." (PMID 35528835, 2022).
dyslipidemia (continued). "Pemafibrate, a novel selective PPARα modulator, amends NASH histological features in mice and serum alanine aminotransferase (ALT) in NASH patients with dyslipidemia." (PMID 35625520, 2022). "Using the PPARα agonist fenofibrate, an FDA-approved compound used to treat dyslipidemia, axon regeneration after dorsal root crush was increased." (PMID 34586065, 2021). "trans-Vaccenic acid was shown to activate the transcriptional activity of PPARγ and/or PPARα in the JCR:LA-cp rat model of dyslipidemia and metabolic syndrome and in PBMCs." (PMID 31782488, 2020). "It was reported that up-regulated hepatic expressions of PPARα genes and down-regulated SREBP1 genes were thought to be responsible for acute alcohol-induced dyslipidemia." (PMID 31035540, 2019). "FGF21 is a direct target of PPARα, and pemafibrate increases fasting and postprandial FGF21 levels along with improving dyslipidemia in humans." (PMID 31766193, 2019). "In recent times, and as alluded to when discussing dyslipidemia earlier, tocotrienols have been shown to be important in activating PPAR family of nuclear receptors, namely PPARα, PPARγ and PPARδ." (PMID 29387138, 2018). "Dual agonists of PPARα/γ, such as glitazar, have been developed and have recently become available for the combined treatment of T2DM and dyslipidemia." (PMID 30060458, 2018). "Analogously, formononetin and calycosin exhibited strong activation on PPARA and PPARG to correct dyslipidemia and to restore glycemic balance." (PMID 29051733, 2017). "We demonstrated that 8-HEPE has a larger positive effect on metabolic syndrome than EPA and that 8-HEPE acts by inducing PPARα activation in the liver." (PMID 27239345, 2016). "Recently, a new drug, a PPARα/γ dual agonist (Aleglitazar), has been developed for the treatment of patients with T2DM and dyslipidemia." (PMID 27347932, 2016). "PPARα agonists used to treat dyslipidemia have been shown to moderately induce the expression of ACADL and ECHS1 in rat liver, and in rat heart muscle PPARα agonists increase the expression of ECHS1 and reduce the expression of HADHA/B." (PMID 21339799, 2011). "Most importantly, PPARα and γ ligands are FDA-approved and are routinely prescribed for the treatment of several chronic disorders such as hypertriglyceridemia, dyslipidemia, and Type 2 diabetes." (PMID 19789638, 2010). "The effect of PPARα genotype was much stronger in our young adult population than previously reported for older populations, suggesting that younger populations may afford greater sensitivity in identification of the genetic underpinnings of metabolic syndrome sub-phenotypes." (PMID 17705849, 2007). "Notable examples of dual and pan-NR agonists include dual PPARα/γ agonists, such as saroglitazar and NET-144, which improve lipid profiles and insulin sensitivity, offering therapeutic benefits for conditions like T2DM, metabolic syndrome, and MASLD." (PMID 40926269, 2025). "In the present study, chronic HFD feeding suppressed PPARα activation in the liver, which, in turn, downregulated lipolysis and fatty acid oxidation-related gene levels (LPL, CPT-1a, and ACOX1) and ultimately led to hepatic lipid deposition and dyslipidemia." (PMID 39942052, 2025). "The lower expression of genes involved in beta-oxidation, PPARα, PCG1α, and CPT1-αwhich may reflect the dyslipidemia of animals in the high-fat diet groups, with the effects being particularly pronounced in the HFP and HFI groups." (PMID 38822155, 2024). "On the other hand, daidzein, through its dual agonist activity on PPARα and PPARγ, could address T2DM-related dyslipidemia and vascular inflammation and mitigate glucose-induced damage in endothelial cells." (PMID 39768147, 2024). "PPARs involve three subtypes (PPARα; NR1C1, PPARβ; NR1C2, and PPARγ; NR1C3) that control insulin sensitivity, resistance, and lipid homeostasis, making them valid targets for alleviating metabolic syndrome, hyperlipidemia, and diabetes." (PMID 37893218, 2023).